MUC5AC (mucin 5AC, oligomeric mucus/gel-forming)
Diseases named in the same sentence as MUC5AC in open-access papers (continued):
Sharing a sentence is not in itself a finding about the gene and the disease.
tumor (continued). "In addition, MUC5AC-deficient lung tumors show reduced tumor angiogenesis, suggesting that MUC5AC is involved in angiogenesis." (PMID 40371640, 2025). "Recently, DUX4 and MUC5AC were introduced as helpful diagnostic stains; the latter is reported to be typically expressed in scattered tumor cells and—despite its low specificity—may be particularly useful given its wide availability." (PMID 40722508, 2025). "On the other hand, two studies (one using immature CLH2 and one using unknown maturity polyclonal Dako antibodies) associated MUC5AC positivity with decreased tumor size, including one which only showed this association for perihilar ECC." (PMID 36672382, 2023). "There might be a threshold for native MUC5AC, which may identify high-risk groups or a signature of MUC5AC variants (immature and mature) that can help us predict tumor response." (PMID 37175794, 2023). "Among these, MUC4 as well as MUC5AC are highly tumor-associated in BTC." (PMID 36230626, 2022). "In addition, the BTC tumor biopsies of most patients have demonstrated a high MUC5AC reactivity, suggesting the tumor-associated MUC5AC tumor antigen is shed into the blood where it can be detected." (PMID 33806004, 2021). "These tumor categories are the least likely to be the cause of a MUC5AC positive metastasis." (PMID 34547930, 2021). "Serum MUC5AC is a highly particular tumor-associated mucin that could be helpful in the diagnosis and development of therapeutic strategies for biliary tract cancer (BTC), as supported by a previous study." (PMID 33806004, 2021). "Only a limited, non-significant association was observed between the CK7 and MUC5AC expression by tumour cells (p=0.16, Fisher’s exact test), while a significant association was found between MUC5AC and MUC6 expression (p=0.003), with all but one MUC6-positive cancers also showing MUC5AC reactivity." (PMID 33963925, 2021). "Several previous studies have, moreover, shown that MUC5AC immunostaining could offer additional diagnostic information in various tumor types." (PMID 34547930, 2021). "A lower degree of tumor differentiation was associated with a lower expression rate of MUC5AC." (PMID 32843061, 2020). "Additionally, serum MUC5AC was associated with patients with blood type A, larger-sized tumours (>5 cm) and advanced-stage disease." (PMID 30875782, 2019). "Additionally, positive serum MUC5AC was associated with more advanced-stage of the disease and larger tumours (>5 cm)." (PMID 30875782, 2019). "The extrahepatic pancreatobiliary immunohistochemical profile is characterized by expression of a considerable number of markers, including cytokeratins (CK7, CK17, and CK19), mucins (MUC1 and MUC5AC), and tumor-associated epithelial markers (CA19-9, monoclonal CEA, CA125, and maspin)." (PMID 27829047, 2016). "Importantly, overexpression of MUC1, MUC4 and MUC5AC are associated with poor survival and serve as potential tumor markers for PC." (PMID 23102107, 2012). "Biliary MUC4 and serum MUC5AC are highly specific tumour-associated mucins that may be useful in the diagnosis and formulation of therapeutic strategies in BTC." (PMID 18475301, 2008). "Additionally, GCNT3 inhibition may downregulate mucins like MUC1 and MUC5AC, which are linked to tumor progression and metastasis." (PMID 40164585, 2025). "Therefore, a potential association with MUC5AC expression in BTC precursor neoplasms and biliary cell lines could point to interactions of MUC5AC with the cellular machinery involved in biliary carcinogenesis." (PMID 36672382, 2023). "Thus by suppressing immune infiltration and enhancing adhesion and invasion of tumor cell, MUC5AC might be implicated in poor prognosis of the patients with SBC." (PMID 24722639, 2014). "Immunohistochemistry of the tumor cells revealed positivity for MUC5AC and MUC6 and negativity for MUC2 and CDX2." (PMID 41256328, 2025).
tumor (continued). "Following this, we performed a more detailed examination regarding the tumor cells and classified four tumor cell subtypes based on the expression levels of marker genes (C0 MUC5AC+ subtype, C1 NDUFAB1+ subtype, C2 SRGN+ subtype, C3 HEPACAM2+ subtype)." (PMID 40688093, 2025). "CIC oncogenic fusions upregulate its targets—including the ETS variant transcription factor (ETV) 1/4/5 PEA3 family of ETS transcription factors, CCND2, and MUC5AC —promoting tumor development and progression." (PMID 40722508, 2025). "Concordant positive staining of at least one of MUC5AC or PGC was observed between all tumour‐organoid pairs." (PMID 41225774, 2025). "Focal positivity for adenocarcinoma markers such as CK7, MUC5AC in small specimens can be misleading due to the presence of tumor heterogeneity." (PMID 41333217, 2025). "Studies using genetically engineered mouse models of LUAD have shown that the depletion of MUC5AC leads to a substantial reduction in tumor growth and metastasis, underscoring its functional importance in tumor evolution and progression." (PMID 40655139, 2025). "MUC-6, MUC5AC, CAIX, and HNF-1 were immunoreactive, and we discovered germline mutations of MUC-6 and CAIX in tumor tissue." (PMID 40018404, 2025). "We have previously shown that ST6GalNAc-I modulates MUC5AC sialylation, leading to tumor progression." (PMID 40371640, 2025). "Immunostaining of the tumor cells showed MUC5AC, MUC2, trypsin, and BCL1 negativity, leading to the diagnosis of intraductal tubulopapillary carcinoma." (PMID 41235002, 2025). "In contrast, the fractions of tumor cells positive for the classical markers, MUC5AC and CDX2, were higher in tumorin_lobules compared to tumorin_stroma (adjusted p-values: 1.071e-4 and 2.620e-3, respectively)." (PMID 41006303, 2025). "In this study, we identified the role of ST6GalNAc-I in tumor angiogenesis and liver metastasis through modulation of the glycoproteins MUC5AC and VCAN-V1." (PMID 40371640, 2025). "MUC5AC was highly positive in gender, depth of tumor invasion, WHO grade, TNM, lymph metastasis, and lymphatic invasion." (PMID 39886661, 2024). "In colorectal MAC, MUC1 and MUC13 are transmembrane mucins, while MUC2 and MUC5AC are secreted gell-forming mucins resistant to tumor cell death and form an immune infiltrating barrier." (PMID 38443703, 2024). "The overexpression of mucin proteins, such as MUC1, MUC2, and MUC5AC in MCA tumors that form a mucous layer protects tumour cells against immunotherapy." (PMID 38778448, 2024). "Intriguingly, depletion of MUC5AC in brain-tropic cells led to significant reductions in intracranial metastasis and tumor growth, and improved survival following intracardiac injection, in contrast to the observations in the control groups." (PMID 38825648, 2024). "MUC5AC exerts its effects by interacting with various transmembrane-associated proteins, including CD44, integrin β4, and integrin β5, during different tumor events." (PMID 38825648, 2024). "Immunohistochemically, tumor cells were positive for both MUC5AC and MUC6, while pepsinogen-I and H+/K+-ATPase were both negative." (PMID 38583117, 2024). "All of the tumor tissues had high levels of MUC5AC expression, which have been reported to express in metaplastic and cancer cells." (PMID 38280869, 2024). "There were increases in epithelial-to-mesenchymal transition, tumor invasiveness, and metastasis phenotypes in tumors with high MUC5AC expression." (PMID 38825648, 2024). "The Helicobacter genus was found to be enriched in tumors with a null mucin phenotype compared to the other phenotypes and in tumor samples with low MUC5AC expression." (PMID 37085819, 2023). "As a note, among biliary neoplasms (benign or malignant), MUC5AC positivity is sometimes used to label neoplasms as “gastric”, “gastric foveolar”, or “pyloric” subtypes because MUC5AC was traditionally seen as a gastric mucin." (PMID 36672382, 2023).
tumor (continued). "In orthotopic models, the mean tumor to background ratio was 1.787 (SD ± 0.336), and immunohistochemistry confirmed the expression of MUC5AC within tumor cells." (PMID 37241027, 2023). "MUC5AC staining was identified in 44% of CACs, 9 adenocarcinomas with positivity in more than 50% of the tumor (extensive expression) and 16 with focal expression." (PMID 37240002, 2023). "We found that 25.0% intestine- and 37.8% esophagus-specific proteins, such as ELF3 and EPHA2, respectively, were upregulated in the tumor tissues, whereas 77.1% stomach-specific proteins, such as MUC5AC, were downregulated." (PMID 36788224, 2023). "We discuss the clinical evidence surrounding the use of MUC5AC when detected in BTC patients’ tumor tissue and blood and its potential use in managing these cancers." (PMID 36672382, 2023). "A humanised anti-MUC5AC antibody was labelled with 225Actinium (Ac) for targeted radionuclide therapy and demonstrated efficacy to suppress tumour growth in mice." (PMID 35892707, 2022). "To summarize, low levels of KChIP3 promote mucin secretion, which is even more dramatic in tumours with high expression of MUC5AC." (PMID 35131032, 2022). "MUC5AC was found to be negatively expressed in cases of low-grade neoplasia of epithelial cells and high-grade neoplasia of epithelial cells, indicating that MUC5AC can be used as a marker for malignant transformation of gastric mucosal epithelium." (PMID 33777138, 2021). "Overall, 44 of 111 (39.6%) tumor categories showed a detectable MUC5AC expression with 28 (25.2%) categories showing at least in a small proportion strong positivity." (PMID 34547930, 2021). "Likely reasons for discrepant results include the use of different antibodies, IHC protocols, and cut-off levels or scores to define MUC5AC positivity as well as the composition of the tumor cohorts." (PMID 33373033, 2021). "Twenty-one cases of GA-FGM (21/25, 84.0%) had foveolar type tumor (MUC5AC-positive) on the surface (and were therefore ‘exposure’ type lesions)." (PMID 34268625, 2021). "That MUC5AC is broadly expressed across different tumor entities limits its use in the distinction of cancers of different origins." (PMID 34547930, 2021). "Further research indicated that SNHG16 constitutes a novel prognostic marker that promotes tumor formation and metastasis in vivo and in vitro by sponging miR-146a, further inducing MUC5AC expression in NSCLC." (PMID 33435953, 2021). "MUC5AC immunostaining was cytoplasmic and sometimes showed a tendency towards particular strong staining at the apical pole of tumor cells." (PMID 34547930, 2021). "Our highly standardized analysis of 111 human tumor types and subtypes resulted in a ranking order according to the prevalence of MUC5AC expression." (PMID 34547930, 2021). "Our comprehensive analysis of >100 tumor entities identified 44 tumor types and subtypes that at least occasionally express MUC5AC." (PMID 34547930, 2021). "IHC staining of A549 scramble lung xenograft tumor tissue sections exhibited high expression of both ST6GalNAc‐I and MUC5AC compared to ST6GalNAc‐I KO xenografts." (PMID 33792183, 2021). "This review aims to understand the current evidence on the clinical significance of MUC5AC expression in PDA-tumor tissues and evaluate its use as a potential molecular biomarker (specifically as predictive, prognostic, monitoring, and response)." (PMID 34205412, 2021). "We attempted to study the expression pattern of native MUC5AC in PDA from 45 patients (25 patients with resectable tumor and 20 patients with metastatic tumor) using CHL2 Mab." (PMID 34205412, 2021). "Retrospective studies on PDA tumor tissue (detected by immunohistochemistry or IHC)) have investigated the prognostic value of MUC5AC expression but were equivocal." (PMID 34205412, 2021).
tumor (continued). "It appears that both CK7 and MUC5AC metaplastic markers were largely expressed in cancers, being present in 52% and 44% of cases, respectively, while as many as 67% of tumours (35 cases) showed at least one of the two markers and 29% (15 cases) both markers." (PMID 33963925, 2021). "BPN tumor cells normally express high levels of transcripts that mark surface mucous cells in the stomach, such as Muc5ac and Gkn1." (PMID 33821796, 2021). "Mucin4 (MUC4), MUC5AC and bile globular membrane (BGM) are highly specific tumor-associated proteins, which are two carrier proteins of CA19–9 in bile tract." (PMID 33962560, 2021). "In this study, we evaluated the potential of tumor-associated glycans Lea/c/x, sdi-Lea, sLea, sLex and sTn, and mucins MUC1 and MUC5AC as a molecular imaging target for PDAC using a semi-automated, machine-learning-based image analysis workflow." (PMID 34830932, 2021). "A multivariate analysis showed that dMMR status and tumor localization predicted MUC5AC expression independently (p < 0.0001 each)." (PMID 33373033, 2021). "Studies have shown that MUC5AC is also expressed in several cancer types suggesting a potential utility for the distinction of tumor types and subtypes." (PMID 34547930, 2021). "The mice with Scr-MUC5AC cell lines showed a significant increase in tumor volume as well as tumor weight compared to the Sh5AC group." (PMID 32098629, 2020). "sLea is overexpressed on a wide variety of tumor-associated glycoproteins, including mucin-1 (MUC1), MUC5AC, and MUC16 (CA125)." (PMID 33371487, 2020). "MUC5AC expression was seen in tumour cells in the superficial part of the gastric wall, whereas tumour cells positive for MUC6 or PCS III were more frequently found in deeper parts of the wall." (PMID 32488651, 2020). "Higher tumor burden was observed in the MUC5AC-expressing parental group at both 20 and 50 days as compared to animals bearing KO cells." (PMID 32098629, 2020). "Deletion of Mir181ab1 greatly reduced tumor weight and decreased PanIN lesions (assessed by MUC5AC)." (PMID 31874105, 2020). "Upregulation of MUC5AC expression was observed upon 5-fluorouracil (5-FU) treatment, and inhibition of MUC5AC enhanced tumor cells sensitivity to 5-FU." (PMID 32098629, 2020). "MUC5AC is physiologically found in the respiratory tract, stomach and gynecologic sites (endocervix and endometrium) and is present in many tumor types." (PMID 33266161, 2020). "Kaplan-Meier analysis showed a significant (p < 0.001 and p < 0.006) decrease in overall as well as disease-free survival in patients with high MUC5AC expression, suggesting its tumor-promoting role in CRC." (PMID 32098629, 2020). "The findings provide novel therapeutic strategies for targeting the MUC5AC gene in tumor tissues or the anti-MUC5AC antibody in serum, benefiting potential CRC patients with precision medicine." (PMID 32695780, 2020). "The presence of MUC5AC indicated that the tumor differentiated to the foveolar epithelium and fundic glands." (PMID 31165461, 2019). "Overall, the proteins with lower orders of magnitude were analyzed, and tumor marker proteins, such as MUC5AC, MUC1, and CEA, were quantified with high intensity in the dataset." (PMID 29713252, 2018). "Immunohistochemical and immunofluorescent evaluation was conducted to characterize organoid expression of tumor markers Maspin, Muc5ac and CRR9, pancreatic marker PDX1 and gastroenteropancreatic and hepatobiliary epithelial marker CK19." (PMID 29587663, 2018). "The positive staining of MUC5AC was mainly located in cytoplasm and cell nucleus of tumor cells in ccRCC specimens." (PMID 28938681, 2017).
tumor (continued). "In normal goblet cells, AGR2 is required for folding and processing of secreted (MUC5AC) and membranous mucins (MUC1, MUC2, MUC5B;) which have also been implicated in various tumor-promoting processes." (PMID 29267283, 2017). "As in the KFCkY model, YFP-negative low-grade PanIN-like lesions positive for AB/PAS and Muc5AC were observed in close proximity to the tumor." (PMID 29069604, 2017). "Immunofluorescence analysis of the xenograft tumour derived from one of these clones revealed cells expressing the Clara cell marker SCGB1A1, and cells expressing the goblet cell marker MUC5AC, in addition to p63-positive basal cells in the tumour tissue." (PMID 28380052, 2017). "MUC2, MUC5AC, and MUC6 were significantly associated with MMR status and tumor border configuration." (PMID 27298226, 2016). "Several types of mucin (MUC1, MUC3, MUC4, MUC5AC) and glycoprotein tumor antigens such as CA19-9 can be expressed in PDAC." (PMID 27267993, 2016). "The immunohistochemical staining showed some interesting features pointing to differentiation in expression of MUC5AC according to tumor cell differentiation grade." (PMID 26075384, 2015). "We did not observe any changes in levels of amylase or cytokeratin 19, or the mucins MUC1, MUC2 or MUC5AC in rapamycin-treated KC PTEN tumours." (PMID 24717934, 2014). "MUC5AC expression was marginally related to tumor location (p = 0.063) and lymph node metastasis (p = 0.059)." (PMID 24722639, 2014). "MUC1 and MUC4 stained the apical portion of glandular tumor cells and the membrane of intermediate and epidermoid tumor cells while MUC2 and MUC5AC stained the cytoplasm of glandular, mucous, and intermediate tumor cells." (PMID 24367734, 2013). "CLH2 is reactive with the peptide core of the tandem repeat domain, and is likely a cryptic epitope within the Capan-1 tumor-derived MUC5AC." (PMID 24257318, 2013). "The normal gastric mucosa isolated from tumor-affected stomachs was divided into surface versus gland material and thereby MUC5AC was separated from MUC6." (PMID 22563496, 2012). "Mucins isolated from healthy stomachs and tumors tended to be less potent ligands for H. pylori J99 than mucins from tumor-adjacent tissue, even when MUC5AC and Leb amounts were similar." (PMID 22563496, 2012). "To clarify effect of MUC5AC on tumor, we tried to test it using mouse model in vivo, because our in vitro study has the limitation with regard to true tumor microenvironment." (PMID 20492722, 2010). "The expression of MUC5AC was weak in OT and SC tumours, with traces in the cell line and normal human pancreas." (PMID 14760381, 2004). "On confocal analysis, MUC5AC was strongly colocalized with VCAN-V1 in A549-scramble cells in the tumor matrix region, but this localization was completely abrogated in MUC5AC-KD cells, suggesting that MUC5AC modulates VCAN-V1 for tumor matrix remodeling during angiogenesis and tumor development." (PMID 40371640, 2025). "Notably, the heterogeneity of EPCs, particularly the identification of four distinct tumor cell subtypes (C0 MUC5AC+, C1 NDUFAB1+, C2 SRGN+, and C3 HEPACAM2+), highlighted the complexity of GC biology." (PMID 40688093, 2025). "Similarly, MUC5AC+ tumor cells establish connections with other cells via the MDK-NCL receptor-ligand pair." (PMID 40124374, 2025). "This not only enhances the adhesion of tumor cells to the extracellular matrix by catalyzing the sialylation of mucins such as MUC5AC, but also mediates tumor immune escape by inducing the expression of sTn antigen, thereby promoting cancer cell proliferation and affecting the prognosis of patients." (PMID 40852041, 2025). "In addition, we showed that ST6GalNAc-I/MUC5AC mediates lung endothelial cell proliferation and migration, suggesting that the ST6GalNAc-I/MUC5AC axis is required for tumor angiogenesis." (PMID 40371640, 2025).